CD4 (CD4 molecule)
Diseases named in the same sentence as CD4 in open-access papers (continued):
Sharing a sentence is not in itself a finding about the gene and the disease.
cancer (continued). "There is growing evidence that anti-HER2 CD4+ T helper cell (Th1) immunity plays a crucial role in cancer therapy and weak Th1 responses are suggestive of poor treatment response and prognosis." (PMID 27766079, 2016). "MiRNAs have shown significant role in CD4+ T cell differentiation, maturation and to develop plasticity during cancer and infectious diseases." (PMID 26941729, 2016). "Cancer patients had higher levels of BATF+CD4+ T cells, PD-L1+CD8+ T cells and CTLA-4+CD8+ T cells compared to healthy donors." (PMID 28936253, 2016). "Previous in vivo studies have shown ALT-803 to be a potent immunostimulatory complex, promoting the activation and proliferation of NK cells and CD8+ T cells against cancer and infectious disease, with minimal induction of CD4+ T cell proliferation." (PMID 27082643, 2016). "Laricitrin decreases expression of IL-10 in cancer-conditioned DCs, and subsequently switches CD4+ T cell response from Th2 to Th1 in vitro and in vivo." (PMID 27833081, 2016). "Activation of FPRL-1 by LL-37 has been implicated in immune surveillance against neoplastic transformation, wherein cells of the immune system such as natural killer lymphocytes (NKs) and type 1 CD4+ T lymphocytes recognize and destroy cancer cells." (PMID 26395996, 2016). "Our findings, therefore, provide new possibilities for the development of an immunization tool aimed against diseases such as viral, microbial as well as cancers that also require potentiation of CD4+ and, more importantly, CD8+ T cell responses." (PMID 27251373, 2016). "Other studies have also focused on CD4+ T-cells as effectors of cancer immunotherapy, as lymph nodes harbor a mixed population of CD4+ and CD8+ T-cells." (PMID 27657129, 2016). "The cancer patient 1-derived CD4+ T cell lines that were harvested from the induction culture responded to the CDCA155-78 and LY6K172-191 peptides in an HLA-DQ or HLA-DR-restricted manner." (PMID 27050553, 2016). "Here we show that co-expression of two cytokine members of the common cytokine receptor γ-chain family, IL-21 and IL-7, in whole-cell cancer vaccines boosts antitumor immunity in a CD4+ and CD8+ T cell-dependent fashion." (PMID 27571893, 2016). "The increase in IL-10 secretion in LICRC patients was further confirmed by measuring IL-10 secretion in the whole CD4+ T cell population, thus confirming the immunosuppressive milieu in cancer patients." (PMID 26885615, 2016). "The polarization of CD4+ T lymphocytes is another possible relevant immunological parameter correlated to patients’ survival in several cancers." (PMID 27782813, 2016). "While the percentage of CD4+ T cells was similar between cancer patients and healthy donors, cancer patients had 180% higher levels of BATF+CD4+ T cells (p=0.0029)." (PMID 28936253, 2016). "In contrast, the presence of CD4+ cells in different types of cancer has yielded contradictory results regarding prognosis." (PMID 27463005, 2016). "Microbial dysbiosis resulting in major shifts in intestinal commensal bacteria often result in changes in CD4+ T lymphocyte populations in vivo, leading to an influx of Th17 cells, chronic inflammation, and eventually cancer." (PMID 31456935, 2016). "A recent consensus statement by The Association for Cancer Immunotherapy (CIMT) immunoguiding program (CIP) concluded that minimally required markers of human Treg are CD3, CD4, CD25, CD127, and Foxp3." (PMID 27330811, 2016). "HIV infection, cancer, radiotherapy, and chemotherapy lower immunity through reduction in CD4 cell counts." (PMID 26136407, 2015). "Approaches that aim to break through such an obstacle would be beneficial to the treatment of cancer patients, by means of eliminating CD4+CD25+Treg cells with a specific antibody." (PMID 25593198, 2015). "Recently Foxp3+CD4+ T cells became an object of great interest in studies of different cancer types as well as in NSCLC." (PMID 26604855, 2015).
cancer (continued). "Accurate methodology and understanding of the CD4+ T cell response against survivin is necessary for the development of cancer immunotherapies against survivin expressing tumors." (PMID 25992291, 2015). "Several approaches have been developed to stimulate antitumor CD4 T cell immunity, during therapeutic cancer vaccines." (PMID 26350591, 2015). "CCL21 participates in the proliferation of CD4 T cells, kidney mesangial cells, and various cancer cells." (PMID 25798926, 2015). "The TCM/TEM ratio of memory CD4 T cells and their function can also be critical in determining T cell responses to cancer cells." (PMID 25803808, 2015). "Most patients were males (11/13), median age at cancer diagnosis was 55 years, and median CD4 cell counts was 299 cells /mm3." (PMID 26642314, 2015). "The shift in CD4+/CD8+ ratio of TIL in different cancers can be due to the declined CD4+ T cells and/or to the increased CD8+ T cells." (PMID 25605488, 2015). "Although most CD4+ T cells require antigen cross-presentation by APCs to produce Th1 cytokines, our observations indicated that TR-CD4 can bypass the requirement for APCs and directly delay cancer cell growth." (PMID 26447332, 2015). "Perhaps, because of these observations, attempts to exploit CTLs, TILs, and CD4+ Th1 cells have been the predominant immunotherapeutic approaches for cancer." (PMID 26217587, 2015). "Several studies have reported the changes in the frequency of CD4+ and CD8+ T cells and the CD4+/CD8+ ratio in the peripheral blood of patients with different types of cancers." (PMID 25605488, 2015). "Negative and statistically significant correlations between CD28 expression and percentages of CD4+NKG2D+ T cells were observed in both cancer patients (Spearman ρ = -0.859; p < 0.001) and healthy controls (Spearman ρ = -0.522; p = 0.003)." (PMID 26486970, 2015). "Although Foxp3+CD4+ T cells can potentially promote cancer progression, they can also attenuate inflammation." (PMID 26604855, 2015). "HLA molecules harbor cancer antigens that promote the binding of DCs to receptors on CD8+ killer and CD4+ helper T cells leading to an immune response against cancer cells." (PMID 26690485, 2015). "These recent observations pointed out once more, the role of CD4 T cells in antitumoral immune response and the interest in targeting them to increase clinical benefit of cancer vaccines." (PMID 26350591, 2015). "In the spleen, TT significantly decreased %CD4+CD44hiCD25+ lymphocytes compared to the mock-treated cancer group (CA) and control (PBS)." (PMID 26113869, 2015). "In5 derived crude extract to affect the viability of the cancer cells tested while sparing naïve and activated CD4 T-cells." (PMID 26734508, 2015). "The high mortality rate in this study is attributed to advanced age at diagnosis, late presentation, HIV seropositivity, CD4+ count below 200 cells/μl, stage of the cancer and presence of metastasis at the time of diagnosis." (PMID 26654449, 2015). "HD1B cells showed much stronger immunosuppression on CD4+ T cell proliferation and function in vitro, and enhanced cancer cells proliferation." (PMID 25807535, 2015). "The role of CD4 Th cells in cancer vaccine is supported by early studies in animals showing that the depletion of CD4 T cells inhibited vaccine-induced protective immunity." (PMID 26350591, 2015). "Activation of CD4 T cells is a reaction to challenges such as microbial pathogens, cancer and toxins that defines adaptive immune responses." (PMID 26641092, 2015). "Survivin also possesses HLA class I and II-restricted epitopes, and have been show to induce robust CD4+ T-cell responses in the majority of vaccinated cancer patients." (PMID 26807308, 2015). "Instead, a list of potential peptides (survivin peptides 17–31, 90–104, 96–110, 128–142) to be included in cancer vaccine studies was given based on their immune prevalence and ability to elicit both a CD4+ and CD8+ response." (PMID 26807308, 2015).
cancer (continued). "Contrary to the effector T cells, CD4+CD25highTregs are resistant to FasL-induced apoptosis and cancer-derived EVs have been reported to stimulate the expansion and suppressive functions of Tregs." (PMID 28936238, 2015). "In 2005, the WHO-European Organization for Research and Treatment of Cancer identified the disease as a CD4+/CD56+ hematodermic neoplasm due to its derivation from a plasmacytoid dendritic cell precursor." (PMID 25780395, 2015). "Cancer patients containing low levels of CD4/CD8 ratio (≤1.2) had significant very low mortality and relapse with cumulative hazards below 0.05 throughout the entire 5 year follow-up." (PMID 25968569, 2015). "While we failed to observe significant changes in coinhibitor expression on endogenous CD4+ T cells in control vs. cancer animals at baseline, endogenous CD8+ T cells in the control group exhibited increased expression of PD-1." (PMID 24796533, 2014). "In cancer patients, CD4+ T cell responses were detected to all seven MSLN-derived peptide pools, suggesting that the response is directed toward a broad repertoire of epitopes within the MSLN protein." (PMID 24520352, 2014). "The cytokine production in turn can activate the generation of cytolytic CD8+ T-cells or act directly against the cancer, and thus, CD4+ effector memory cells are crucial for the generation of antitumor immune responses." (PMID 24498197, 2014). "We found that the population of LAP-positive CD4+Foxp3+ Tregs significantly increased in peripheral blood and cancer tissues of CRC patients as compared to that in the peripheral blood and tissues of healthy subjects." (PMID 25268580, 2014). "The inflammatory nature of many cancers creates an immunosuppressive environment that leads to suppression of DC-instructed effector CD4+ and CD8+ T cell responses." (PMID 25369453, 2014). "The activation of antigen-presenting cells (APCs, i.e., CD4+ T cells and dendritic cells) by CD40L present on CD4+T cells enhances the specific anti-cancer immune response." (PMID 25117071, 2014). "A remarkable higher proportion of cancer patients had CD4 T-cell counts <200 c/mmc at time of diagnosis (45.2% vs 13.3%, p<0.0001)." (PMID 25394156, 2014). "The results thus indicate that antigen-specific CD4+ T cell help is indeed beneficial for the induction of a strong cancer-specific immune response, which is in line with a number of other studies." (PMID 24782868, 2014). "During the cancer progression, CD4+ cells undergo apoptosis leading to the impaired CD4+and CD8+cells mediated antitumor immunity and therapies which restore the CD4+ mediated signaling are known to act as immune activators." (PMID 25248151, 2014). "In this study we therefore analyzed the potential function of C/EBPα in lymphopoiesis with particular emphasis on a role of C/EBPα in PD-1+ CD4+ T cells and in age/cancer-dependent immunosenescence." (PMID 24404186, 2014). "The results demonstrate that the frequency of circulating anti-MSLN specific CD4+ T cells in cancer patients were significantly higher than that observed in the benign pancreatic disease patients (p = 0.0053) and normal controls (p = 0.0004)." (PMID 24520352, 2014). "Previous studies have shown the relevance of this NeuGcGM3 in cancer progression and its capability of modulating CD4 expression on T cells." (PMID 24639871, 2014). "The TG6113 T2/Onc2 strain was chosen because it has the highest copy number of transposons within the donor concatemer of any existing SB strain, and the CD4-Cre model was chosen due to its long latency relative to other T2/Onc2-induced malignancies." (PMID 25526783, 2014). "A comprehensive model of the CD4+ cells has the potential to provide substantial insight into cancer treatment, immunotherapy, and cellular biology." (PMID 25538703, 2014).
cancer (continued). "Several studies have suggested a negative impact of MDSC in the effector cells of the immune system of cancer patients, including NK cells, DCs, both lymphocytic populations (CD4+ and CD8+ T cells), B cells, and monocytes." (PMID 25436215, 2014). "It is present not only on the surface of activated CD4+ T cells, B cells, blood platelets, monocytes, and natural killer (NK) cells but also on cancer cells." (PMID 25117071, 2014). "CD4+ helper T lymphocytes (HTLs) play a critical role in anti-cancer immunity by promoting the induction and survival of CD8+ CTLs." (PMID 25240937, 2014). "(c) Mesothelin-specific CD4+ T cell response is directly inhibited by elevated IL-10 in cancer patients." (PMID 24520352, 2014). "These probes were then used to quantitate and provide additional phenotypic characteristics of circulating CD4+ T cells in HLA-DR4+ cancer patients." (PMID 25325015, 2014). "We initially compared the mean frequencies of Tregs and Teffs within CD4+ T cells between 10 cancer patients and 7, age and sex matched, healthy donors." (PMID 24957270, 2014). "Depending on the nature of the pathogen or cancer type, antigen-specific B cell, CD4+ and/or CD8+ T cell responses are critical to confer protective immunity." (PMID 25137039, 2014). "Taken together, our data suggest that pNGVL4a-hCRTE6E7L2 DNA vaccination via electroporation warrants testing in otherwise healthy patients and those with compromised CD4+ T cell immunity to treat HPV-16-associated anogenital disease and cancer." (PMID 24594273, 2014). "Our data revealed differences in the constellation of coinhibitory molecules co-expressed on antigen-specific CD8+ T cells vs. endogenous polyclonal CD4+ or CD8+ T cells in Listeria-infected animals in the setting of cancer." (PMID 24796533, 2014). "The enrichment of CD4+Foxp3+LAP+ Tregs in the peripheral blood of CRC patients can be potentially used for monitoring cancer immunotherapy in clinical settings." (PMID 25268580, 2014). "The comparison between CRC patients and healthy donors (HD) revealed that LAP expression in CD4+Foxp3+ T cells isolated from PBMCs was significantly increased in cancer patients (CRC: 18.8%±9.2% vs. HD: 7.8%±3.3%)." (PMID 25268580, 2014). "Immunity against certain (persistent) intracellular bacteria and viruses as well as most cancers, however, relies highly on the activation of antigen-specific CD4+ and CD8+ T cells, which requires different types of vaccines." (PMID 25137039, 2014). "Collectively, these findings provide rationale for induction of CD4 T cell responses with cancer vaccines, either alone, or in combination with MHC-I-restricted epitopes." (PMID 24690990, 2014). "C-26 carcinoma cells challenged Balb/c mice had a decrease of CD4+, CD8+, CD19+ as well as CD94+ cells in the spleen compared to PBS treated ones." (PMID 25168124, 2014). "A similar trend, although not being significant, was observed for CD68+ macrophages located in close proximity to carcinoma cells (H3) as well as to FoxP3+(CD4+) T cells (F)." (PMID 24797069, 2014). "Among all cancer cases, the median CD4 count at cancer diagnosis was 244 cells/mm3 (IQR: 109–458), lower than the median CD4 count observed in the overall patient population." (PMID 23705808, 2013). "Cytotoxic CD4+ T-cell activity against MHC II-negative tumors can also be used in cancer immunotherapy." (PMID 22890822, 2013). "Accordingly, it will be important to identify strategies that allow TCRs to mediate CD4 T cell activity, ultimately enabling a broad anti-cancer immune response." (PMID 23970885, 2013). "Nevertheless, it has been well recognized that the detection of immune cells infiltrating tumors, such as memory/effector CD8/CD4 T cells or Treg, correlated with the prognosis in certain types of cancers." (PMID 23533812, 2013). "In general, the participation of CD4+ T cells in immune responses against cancer was assumed to be restricted to a helping manner for the generation of powerful CTL activity." (PMID 24205259, 2013).
cancer (continued). "The role of CD4+ T cells in the generation of therapeutic primary and memory immune responses in cancer diverse immunotherapy settings remains ambiguous." (PMID 24066030, 2013). "HDAC inhibitors have previously shown to induce cell-cycle arrest and apoptosis in cancer and CD4+ T cells and to have anti-inflammatory effects on human monocytes." (PMID 23737814, 2013). "The success of cellular immunotherapies against cancer requires the generation of activated CD4+ and CD8+ T-cells." (PMID 26344346, 2013). "In cancer, inducible (i) or adaptive Treg expand, accumulate in tissues and peripheral blood of patients, and represent a functionally prominent component of CD4+ T lymphocytes." (PMID 23898333, 2013). "Cancer-induced immune cell apoptosis as well as block in maturation from CD4-8- to CD4+8+ and finally to CD4+ and CD8+ effector T cells were also reported." (PMID 24053127, 2013). "Further investigation is needed to determine the precise mechanisms of GILT’s role in cancer pathogenesis and survival as well as other aspects of CD4+ T cell-mediated immunity, especially in regard to anti-pathogen immune responses." (PMID 24409178, 2013). "The influence of CD4+CD25+Foxp3+ regulatory T-cells (Tregs) on cancer progression has been demonstrated in a large number of preclinical models and confirmed in several types of malignancies." (PMID 24133490, 2013). "Clustering analysis identified a potential biomarker predictive of survival across cancer types consisting of the ratio of CD4+ T cells/μl to CD14+HLA-DRlo/neg monocytes/μL of blood." (PMID 25512872, 2013). "In general, exogenous antigens presented by MHC class II molecules are intended for CD4+ T cells, while internal antigens from components of virus-infected cells and cancer antigens are presented on MHC class I molecules for the activation of CD8+ T cells." (PMID 24224170, 2013). "A major line of research pursued a possible instructive role of TGF-ß, a signaling molecule with pleiotropic functions in both immunity and cancer, and in the conversion of CD4+CD25− T-cells to pTreg cells." (PMID 24133490, 2013). "As one of their primary emerging roles as “regulators” of the immune response to cancer, CD4 T cells have been shown to orchestrate and coordinate many facets of both the innate and adaptive immune responses to ensure optimal responses by other lymphocytes." (PMID 23533029, 2013). "Apart from CD8+ cells there is evidence of increased apoptosis among CD4+ T cells in peripheral blood lymphocytes from cancer patients and animal models." (PMID 24053127, 2013). "The inverse relationship between these two cells types has not been explicitly described before and these results suggest that the CD4/CD14+HLA-DRlo/neg monocyte ratio is an important biomarker for cancer prognosis." (PMID 25512872, 2013). "The ability of GalNAc to break immunological tolerance and to aid the generation of a CD4+ T cell dependent humoral immune response is of particular importance in cancer immunotherapy aimed at generating IgG antibodies." (PMID 23189185, 2012). "Specific T cell response to cancer cells and viruses is tightly regulated by regulatory CD4+ cells (Tregs) expressing fork-head box (Fox)-P3 (CD4 + CD25 + FoxP3+)." (PMID 22642942, 2012). "An inverse relationship between circulating IL-7 levels and CD4 T cell counts was consistently found in various clinical settings including cancer and HIV infection, suggesting that IL-7 plays a unique role in maintaining lymphocyte homeostasis." (PMID 23251223, 2012). "Among CT antigens, NY-ESO-1, a SEREX-defined CT antigen, was shown to induce a frequent antibody response in cancer patients, and strong CD4 and CD8 T-cell responses against NY-ESO-1 were also elicited." (PMID 23151147, 2012).